TIMP4 (TIMP metallopeptidase inhibitor 4)
Diseases named in the same sentence as TIMP4 in open-access papers (continued):
Sharing a sentence is not in itself a finding about the gene and the disease.
tumor (32 papers, 2001 to 2026). "In clinical studies, the overexpression of TIMP-1 and TIMP-4 has been associated with a poorer prognosis in many tumours; they activate signalling pathways related to inflammation and fibrosis—for example, mitogen-activated protein kinase (MAPK) pathways." (PMID 38067256, 2023). "Tissue inhibitors of metalloproteinases (TIMPs) are proverbial inhibitors of metalloproteinases and composed of four structurally related members (TIMP1, TIMP2, TIMP3, and TIMP4), associated with tumor invasion and angiogenesis." (PMID 35559040, 2022). "We found that the expression level of LAMA2, TIMP4, and TMTC1 was higher in all TCGA tumours and significantly associated with poor survival." (PMID 37238942, 2023). "Significant correlations were also found between MMP-3 and TIMP-4 levels, and some variables related to patient characteristics and tumour biology, such as menopausal status tumour classification, differentiation grade and E-cadherin presence." (PMID 38203696, 2023). "The main function of TIMPs is to inhibit MMPs, but they also have many other functions; for example, TIMP-4 has a positive correlation with tumor aggressiveness." (PMID 35655767, 2022). "LOX and SNAI2 can regulate the induction of TIMP-4, which can lead to tumor invasion, migration, and VEGF expression." (PMID 35954348, 2022). "Meanwhile, low expression levels of tissue inhibitors of metalloproteinases (TIMP-3 and TIMP-4) were found in all three tumor lines." (PMID 34620867, 2021). "Recent studies have revealed that TIMP4 is involved in the inhibitory effect of various substances on cancer, showing a negative regulatory role in the progression of various tumours." (PMID 34781885, 2021). "Significant correlations were found between MMP‐3 and TIMP‐4 levels, and some of the variables studied related to patient characteristics and tumour biology." (PMID 31568637, 2020). "Considering Ki67 protein, TIMP‐4 levels varied depending on the Ki67 percentage in the tumour, with higher expression in patients with Ki67 percentage score <20%." (PMID 31568637, 2020). "Conversely, KLF4, CXCL2, MAPK3 and TIMP4 were up regulated in normal samples compared to tumor tissues." (PMID 26498364, 2015). "The mechanisms by which the decreased expression of MMP9 and MMP10 and the increased of TIMP4 are responsible for the depressed growth and invasion of tumor cells due to S100A4 silencing, are currently being investigated in our laboratory." (PMID 22200787, 2012). "Similar to TIMP-3, TIMP-4 expression is regulated by promoter methylation in cancer cell lines and tumor samples." (PMID 19025595, 2008). "On the other hand, TIMP-4 can either promote or inhibit tumour progression, depending on the nature of the tumour and mode of delivery." (PMID 15928670, 2005). "TIMP-4 transcripts were predominantly localized to tumour cells, though minor expression was found in vessels." (PMID 11437402, 2001). "TIMP1 emerges as the only consistently overexpressed inhibitor, while TIMP4 appears as a promising prognostic marker with unique MMP correlations that may influence tumor behaviors." (PMID 41718391, 2026). "In addition, TIMP-4 can induce tumor growth and promote tumor progenitor cells, possibly through the activation of the TGF-β and NF-κB protein network." (PMID 35954348, 2022). "Thus, relatively few studies have investigated the role of TIMP4 in tumours, making its role in some tumours unclear in published studies." (PMID 34781885, 2021). "Many of the genes epigenetically silenced by upY-Stat5a carry tumor suppressive functions (e.g., TIMP4, SH3GL2), suggesting upY-Stat5a itself may be involved in hPRLrL+I-driven mammary transformation." (PMID 33772010, 2021). "From SOM to EOT, e.g. during tumor progression on single bevacizumab treatment, weak evidence was observed for increase in the level of five proteins (TIMP-4, MMP-8, EGF, Amphiregulin, and Tissue factor/Coagulation factor III), whereas a decrease was seen in only one protein (CD26)." (PMID 30592740, 2018).
tumor (continued). "Previous work has shown that TIMP-4 negatively regulates the growth of diverse tumor cells." (PMID 26291714, 2015). "TIMP4 inhibits tumor progression by inhibiting cell matrix degradation by endopeptidase MMP-2." (PMID 21909426, 2011). "The expression of TIMP3 and TIMP4 decreased progressively with increasing Gleason score, supporting the classic notion that these inhibitors may be protective in tumour progression." (PMID 15928670, 2005). "The three proteins (MMP-8, TIMP-4 and EGF) that following a decrease during tumor inhibition also showed evidence for an increase during progression are involved in cancer cell survival, proliferation and migration." (PMID 30592740, 2018). "The transcriptomic analysis of the Groft scientific group showed a positive correlation between TIMP1 expression and a negative correlation of TIMP4 expression with tumor grade and malignant behavior, while the expression of TIMP3 and TIMP2 remained unchanged." (PMID 38474106, 2024). "Expression levels of LAMA2, TIMP4, and TMTC1 across TCGA tumours are shown in." (PMID 37238942, 2023). "We found that the expression level of LAMA2, TIMP4, and TMTC1 was higher in all TCGA tumours." (PMID 37238942, 2023). "Similarly, the up-regulation of both anti-angiogenic factors, TIMP-4 and IGFBP3, suggests that NX treatment prevent tumor angiogenesis by controlling the secretome of U87-MG cells." (PMID 29156770, 2017). "With VEGF tumor overexpression, IGFBP-3, PTX-3, and TIMP-4 increased significantly in the plasma." (PMID 27995973, 2016). "Compared to the 10 proteins (GM-CSF, IGFBP-1, IGFBP-3, PTX-3, PDGF-AA, serpin E1, PEDF, TIMP-1, TIMP-4 and uPA) detected in the plasma of MDA-MD-231_WT tumor bearing mice, only 2 (serpin E1 and TIMP-1) were detected in the plasma of MCF-7_WT tumor bearing mice." (PMID 27995973, 2016). "We did not detect Timp4 expression in any tumor by qPCR analysis using three different primer pairs (data not shown)." (PMID 24886479, 2014). "Finally, TIMP‐4 levels were higher for E‐cadherin positive tumours; but it is noteworthy the large increase in TIMP‐4 in E‐cadherin negative tumours after RT." (PMID 31568637, 2020). "Thus, we argue that the proportion of stromal cells in the prostate tissue homogenates does not vary appreciably between benign and malignant tissues, and therefore the reduced expression of TIMP3, TIMP4 and RECK is most likely a functional consequence of tumour–stromal interactions." (PMID 15928670, 2005).
cancer (28 papers, 2005 to 2025). A tumor composed of atypical neoplastic, often pleomorphic cells that invade other tissues. "Silencing of TIMP4 via hypermethylation of its promoter has been reported in other human cancers, with reduced TIMP4 associated with increased angiogenesis." (PMID 35480116, 2022). "Interestingly, another cancer-associated gene, TIMP4, located within an intron of SYN2 and transcribed in the opposite direction, was found to interact with folic acid supplement use and alter risk of CRC." (PMID 37640106, 2023). "Like TIMP2, TIMP4 was found to be up-as well as downregulated in tumors depending on the type of cancer." (PMID 37313172, 2023). "TIMP1 is commonly found in cancer cells and is associated with a poor prognosis; TIMP2 inhibits the mitogenic response of human microvascular endothelial cells to growth factors; and TIMP4 is an MMP inhibitor in human platelets." (PMID 33960555, 2021). "Similar to TIMP-2, it has been found that TIMP-4 is upregulated or downregulated in several types of cancer." (PMID 33419373, 2020). "Recent reports showed that TIMP-4 is also disregulated during cancer invasion and progression of several organs (for instance in reproductive organs) which highlights its potential role as a biomarker or therapeutic target of disease." (PMID 23145060, 2012). "Clearly, additional studies using a wider range and number of samples are needed to draw a conclusion, but, for some tumors, a scenario in which TIMP-4 marks the transition to invasive cancer emerges." (PMID 19025595, 2008). "Studies have also reported that TIMP-4 is expressed in some cancers; however, its role in cancer establishment and/or progression remains unclear." (PMID 36013323, 2022). "MMP26 may promote cancer invasion and metastasis by activating proMMP-9 by cleaving the proenzyme site of Ala93-Met94 and interacting with TIMP4 to promote cancer progression." (PMID 35954348, 2022). "However, TIMP-4 has been shown to inhibit platelet aggregation and to decrease the migration and invasive potential of cancer cell lines." (PMID 35326438, 2022). "Compared with the constant and opposing patterns of TIMP-1 and TIMP-3, variable trends have been reported for TIMP-2 and TIMP-4 in human cancer, which could due to the heterogeneity of the types and stages of cancer." (PMID 33419373, 2020). "In the TIMP2 and TIMP4 co-expression profiles we observed distinct clustering for the carcinomas." (PMID 31882975, 2019). "Since peroxynitrite, via post-translational modifications of target proteins, contributes to cardiovascular injury and cancer, its effect on TIMP-4 could be involved in the pathology of these diseases." (PMID 19025595, 2008). "Finally, it is important to study the potential relevance of the possible new transduction partners of TIMP-4 on cancer progression and to identify the importance of their localization." (PMID 19025595, 2008). "All these results point toward the need to perform additional studies to determinate the relevance of TIMP-4 in cancer invasion and progression, in particular to establish if a positive correlation with prognosis or inverse correlation with invasion in patients can be made." (PMID 19025595, 2008). "Because TIMP-4 may affect the sensitivity of cancer cells to chemotherapy, as suggested by our present work, it would be attractive to perform additional studies to investigate whether patients expressing higher levels of this inhibitor have a better or worse prognosis." (PMID 26291714, 2015). "Thus, analysis of samples at later stages may detect only a TIMP-4 decrease, missing early changes, especially when the studies lack samples from initial cancer stages or normal tissue controls." (PMID 19025595, 2008). "The pan-cancer survival network further enriches the inhibition of matrix metalloproteases (A2M, MMP1, MMP14, MMP3, TIMP4)." (PMID 35106465, 2022).
cancer (continued). "Correspondingly, THY-1 cell surface antigen (CD90), tissue inhibitor of metalloproteinase (TIMP)-4 and SERPIN F1, previously reported to negatively regulate invasion of cancer cells, were found to be downregulated." (PMID 25682871, 2015). "For these reasons, it is not unexpected that TIMP-4 is disregulated during cancer progression of several organs." (PMID 19025595, 2008). "TIMP-4 mutants that lack MMP-inhibitory activity could be helpful in elucidating the MMP-dependence or independence of normal and cancer cells' behavior." (PMID 19025595, 2008). "In contrast, there was significantly decreased expression of MMP2 and MMP23, maspin, and the protease inhibitors tissue inhibitor of metalloproteinase 3 (TIMP3), TIMP4 and RECK (reversion-inducing cysteine-rich protein with Kazal motifs) in the cancer specimens." (PMID 15928670, 2005). "In the present study, we further detected the protein level of TIMPs in human LoVo cancer cells that had been exposed to PGE2, which demonstrated that PGE2 treatment shows no influence on regulating TIMP-1, TIMP-2, TIMP-3 and TIMP-4." (PMID 21859479, 2011).
cardiovascular disease (5 papers, 2013 to 2023). "A study of cardiovascular disease showed that TIMP4 was up regulated in inflammatory processes of human cardiovascular pathology." (PMID 30697482, 2019). "Similar pathological phenomena can occur in other systemic diseases, like cardiovascular disorders, where the recently discovered TIMP4 seems to play a significant role." (PMID 24498922, 2013).
infection (4 papers, 2012 to 2019). The state of being infected such as from the introduction of a foreign agent such as serum, vaccine, antigenic substance or organism. "The number of cells positive for the viral protein E in cells depleted of GIGYF2 or TIMP4 was either similar or higher compared to that of control cells upon YFV or WNV infection, suggesting that these two candidates are dispensable for replication of both viruses." (PMID 30650657, 2019). "TIMP-2, -3 and to a lesser extent TIMP-4 mRNA were constitutively expressed at high levels within the CNS of naïve WT mice, but were not further up-regulated by infection." (PMID 24156369, 2013). "Thus, an imbalance between the circulating levels of specific MMPs and TIMPs—especially increased MMP-1 and MMP-8 to TIMP-4 and decreased MMP-1 and MMP-7 to TIMP-1 and 2—is characteristic of filarial lymphedema in the presence of active infection." (PMID 22679524, 2012). "TIMP-4 levels were lower during the acute phase of infection, persisting as such even when MMP-9 and TIMP-1 have already decreased, until eosinophil meningitis was not definitely recovered, suggesting that TIMP-4 plays a crucial role in the proteolytic balance of BBB damage, in these patients." (PMID 25436884, 2013).
cardiac diseases (1 paper, 2025). "Moreover, the involvement of TIMP4 in atrial fibrosis of patients with cardiac diseases has been extensively studied." (PMID 40809177, 2025).
psychiatric disorder (1 paper, 2024). A disorder characterized by behavioral and/or psychological abnormalities, often accompanied by physical symptoms. "Further exploration is needed to understand the relationship between TIMP4 and mental illnesses." (PMID 38637810, 2024). "Other TIMP4 variations or interactions with different genes may still be relevant to psychiatric disorders." (PMID 38637810, 2024). "Additionally, the study was conducted on a Korean population, and genetic heterogeneity between different populations suggests that the role of TIMP4 in psychiatric disorders may vary across different ethnic groups." (PMID 38637810, 2024). "However, the lack of association with a single SNP does not rule out the potential linkage between TIMP4 and psychiatric disorders." (PMID 38637810, 2024).
TIMP4 also shares sentences with these, for which no sentence is quoted: psoriatic arthritis (3 papers); acute myocardial infarction (2); cardiac hypertrophy (2); colon cancer (2); COVID-19 (2); ischemia (2); pancreatic cancer (2); thyroid cancer (2); angiosarcoma (1); biliary atresia (1); bladder carcinoma (1); cerebral amyloid angiopathy (1); chronic rhinosinusitis (1); Cirrhosis (1); clear cell carcinoma (1); colorectal cancer (1); Coronary Artery Disease (1); dedifferentiated liposarcoma (1); diastolic heart failure (1); dilated cardiomyopathy (1); giant cell arteritis (1); head and neck squamous cell carcinoma (1); Huntington disease (1); Hyperinsulinemia (1); hyperlipidemia (1); idiopathic dilated cardiomyopathy (1); injury (1); intracerebral hemorrhage (1); invasive carcinoma (1); Left ventricular dilatation (1).
A further 29 diseases each share a sentence with TIMP4 in 1 paper.